RNU6-896P (RNA, U6 small nuclear 896, pseudogene)
Gene: Small nuclear RNA gene on chromosome 6 (153,681,447 to 153,681,553, forward strand). Ensembl gene ENSG00000199246.
Homologues: Orthologues: chimpanzee U6 (99% identical), macaque U6 (86% identical). Paralogues in human: RNU6-1019P (89% identical), RNU6-1060P (89% identical), RNU6-41P (89% identical), RNU6-820P (89% identical), RNU6-1303P (88% identical), RNU6-15P (88% identical), RNU6-187P (88% identical), RNU6-1122P (87% identical), RNU6-1152P (87% identical), RNU6-116P (87% identical), RNU6-12P (87% identical), RNU6-13P (87% identical), and 1285 more.